EGFR (epidermal growth factor receptor)
Diseases named in the same sentence as EGFR in open-access papers (continued):
Sharing a sentence is not in itself a finding about the gene and the disease.
cancer (continued). "Gefitinib interacts with the EGFR ATP-binding site and is able to inhibit the abnormal activation of MAPK and PI3K/AKT pathways overexpressed in cancer cells." (PMID 41294857, 2025). "Activation of PI3Kα through direct mutation or by mutation or overexpression of upstream signaling factors (e.g. KRAS, EGFR, HER2) is one of the most common oncogenic events in human cancers." (PMID 41066541, 2025). "Galectin-8 (Gal-8), a carbohydrate-binding protein that promotes cell proliferation by transactivating the EGFR-ERK signaling pathway, is overexpressed in several cancers." (PMID 40209344, 2025). "The JAK‐STAT signalling pathway plays a significant role in the development of different cancers, such as non–small‐cell lung cancer (NSCLC), and impacts how effective EGFR‐TKIs are, as well as the mechanisms by which resistance to these therapies arises." (PMID 40162549, 2025). "EGFR has been identified as a negative regulator of MHC-I expression and antigen presentation in various cancers." (PMID 39820491, 2025). "Several mechanisms have been implicated in TKI resistance in HCC, including activation of EGFR, PI3K/AKT, MAPK, and JAK/STAT3 pathways, EMT, hypoxia, cancer cell stemness and metabolic reprogramming." (PMID 40715090, 2025). "Genomics-driven cancer biology has ushered in a new era of targeted precision regimens, exemplified by AZD9291 in EGFR-mut NSCLC." (PMID 40087771, 2025). "Erlotinib is another reversible EGFR inhibitor, FDA-approved for NSCLC and pancreatic cancer, and is in advanced development for multiple other cancer types, including colorectal." (PMID 40940907, 2025). "Epidermal growth factor receptor (EGFR) plays a considerable role in the proliferation, survival, adhesion, migration, and differentiation of cancer cells, and is an effective target for cancer therapy." (PMID 40172117, 2025). "Signaling pathways such as the epidermal growth factor receptor (EGFR) and the PI3K/AKT pathways are also often dysregulated, promoting OSCC cancer cell growth and survival." (PMID 40427514, 2025). "Given that malignant cells develop resistance to currently used EGFR-TKIs, and PAFR can mediate inactivated PTEN-induced EGFR overactivation, targeting PAFR could be exploited as a potential strategy to overcome EGFR-TKIs resistance in cancer patients having altered/mutated EGFR." (PMID 40160442, 2025). "However, the transcriptional regulation of EGFR gene in cancer cells remains largely unknown." (PMID 41191192, 2025). "This study presents FolTAC-dual, a folate receptor-mediated platform for dual degradation of EGFR/HER2 and PD-L1/VISTA, offering a strategy to overcome drug resistance and enhance antitumor immunity for cancer treatment." (PMID 41038820, 2025). "The HER receptor family, comprising ERBB1 (EGFR), ERBB2, ERBB3, and ERBB4, plays a pivotal role in tumorigenesis and cancer progression." (PMID 40846695, 2025). "We discovered and validated that concurrent targeting of FYN, along with other tyrosine kinases such as IGF1R, EGFR, or ABL2 can synergistically eradicate TNBC and impede cancer growth." (PMID 40243589, 2025). "Collectively, our work uncovers Ephrin A1 as a functional ligand of EGFR and highlights the potential role of the Ephrin A1/EGFR/EMT regulatory axis in cancer metastasis." (PMID 39838173, 2025). "Epidermal growth factor receptor (EGFR) and vascular endothelial growth factor A (VEGF-A) have been shown to contribute to cancer cell survival and have been identified as potential therapeutic targets for advanced OC." (PMID 40969763, 2025). "PLA-based nanoparticles are used by conjugating antibodies (e.g., trastuzumab, cetuximab) that target cancer cell surface receptors such as HER2 and EGFR (epidermal growth factor receptor) to their surface." (PMID 41155989, 2025). "While immune checkpoint inhibitors (ICIs) have transformed cancer care, their efficacy in EGFR-mutant NSCLC progressing on EGFR TKIs is generally limited." (PMID 39941826, 2025).
cancer (continued). "First, some upstream components, such as EGFR, other RTKs, and Ras, activate multiple downstream effectors, in addition to the Raf-MEK-Erk arm, including cancer promoting components (e.g., the PI3K-AKT/PKB pathway, RalGDS, PKCε, PKCζ, Src;." (PMID 40394416, 2025). "The absence of ABD shifts TNS4’s function toward signal amplification in focal adhesions, stabilizing oncogenic receptors like EGFR and promoting EMT and invasion, thus carrying out predominate oncogenic functions across carcinomas." (PMID 40906372, 2025). "The discovery of the epidermal growth factor receptor (EGFR) and the possibility of using it as a therapeutic target has changed the natural history of many patients suffering from cancer." (PMID 38781107, 2024). "The epidermal growth factor receptor (EGFR) is one of the best known plasma membrane receptors and has been extensively investigated for decades as a cancer therapeutic target." (PMID 38378560, 2024). "Erlotinib is a quinazoline derivative inhibitor of the EGFR TK activity, that is used in the treatment of non-small cell lung cancer (NSCLC), pancreatic cancer, and several other types of cancer." (PMID 39496648, 2024). "The epidermal growth factor receptor (EGFR), a crucial component of cellular signaling pathways, is frequently dysregulated in a range of cancers." (PMID 39652601, 2024). "CAR exosomes, released from EGFR or HER2 scFv-transduced CAR-T cells, induce potent antitumor inhibition in target cancer cell lines and solid tumor xenografts." (PMID 38589859, 2024). "EGFR, HER2, and MCSP are all cell-surface receptors commonly deregulated in cancer, and PD-L1 is an immune checkpoint receptor." (PMID 38828721, 2024). "The patient's cancer responded to rechallenge with BRAF- and EGFR-targeted therapy with a rapid decline in CA19-9 levels, BRAF-V600E allele frequencies (0.3%-0.4%), as well as a radiographic response of the new lesions." (PMID 39626159, 2024). "Enriched gains spanned known cancer and TGCT drivers including MYC (8q11-q24), EGFR (7p11.2), and BRAF (7q34)." (PMID 39461959, 2024). "We expand on this early work here by analysis of the interactome for a PRM from each of the RTKs; EGFR, FGFR2 and HER2, in cell lines derived from four cancers that together represent a diverse range of histological subtypes." (PMID 39165974, 2024). "Saponins have been reported to inhibit various signalling pathways, such as PI3K/AKT, AKT/MAPK, EGFR/PI3K/AKT, PI3K/AKT/mTOR, and RNF6/AKT/mTOR, which leads to its cytotoxic and apoptotic properties on various cancer cell lines." (PMID 39519799, 2024). "However, according to the Multinational Association for Supportive Care in Cancer (MASCC) Skin Toxicity Study Group, which is comprises international, interdisciplinary experts in dermatology, oral retinoic acid is recommended for the treatment of skin disorders caused by the use of EGFR‐TKIs." (PMID 38379420, 2024). "The simultaneous inhibition of EGFR and RAS/mTOR was demonstrated to provide a synergistic antitumor effect in various human cancers." (PMID 38396679, 2024). "i)We provide extensive evidence of the HB-EGF, EGFR, and MAPK pathway activation across multiple pairs of cancer cells and fibroblasts." (PMID 39262776, 2024). "EGFR-TKI sensitivity was evaluated by assessing the proliferation, clonogenic survival and metastatic capability of cancer cells with treatment with gefitinib." (PMID 38872157, 2024). "Currently, EGFR and RAS proteins, which are both aberrantly activated in a wide range of human cancers, are regarded as central targets for anticancer drug development." (PMID 38374954, 2024). "Membrane receptor inhibition is a targeted approach in cancer therapy that focuses on blocking specific receptors, such as HER2 and EGFR, which are involved in cellular growth and differentiation signaling." (PMID 39685591, 2024).
cancer (continued). "Thus, EGFR inhibitors such as Gefitinib and Erlinotib that have an acceptable safety profile and have been clinically used in cancer chemotherapy since their FDA approval in the early 2000s, might be considered for repurposing in the treatment of renal pathologies." (PMID 39234105, 2024). "The differential expression of PIK3R1, AKR1C3, EGFR, ESR1, PIK3CD, CYP3A4, and CYP19A1 across various cancer types and stages illuminates their potential as biomarkers for cancer progression and prognosis." (PMID 39204124, 2024). "Epidermal growth factor receptor (EGFR), one of the most studied receptor kinases, is a drug target for cancer therapy, because its kinase activity correlates with tumorigenicity." (PMID 39335579, 2024). "These compounds target various glycolytic components and represent potential therapeutic avenues for overcoming EGFR-TKI resistance and inhibiting cancer cell growth." (PMID 38255882, 2024). "LRIG1 inhibits epidermal growth factor receptor (EGFR) signaling and is downregulated in several forms of cancer." (PMID 38426087, 2024). "Regarding KEGG pathways, the overlapping genes exerted a considerable influence on pathways including EGFR tyrosine kinase inhibitor resistance, PI3K-Akt signaling pathway, Central carbon metabolism in cancer, and proteoglycans in cancer." (PMID 39149033, 2024). "In the development and progression of cancer, AKT1, JUN, IL6, SRC, EGFR and BCL2 plays a critical role." (PMID 39011503, 2024). "Cholesterol can activate the PI3K/AKT pathway by binding to and stabilizing receptor tyrosine kinase (RTK), particularly epidermal growth factor receptor (EGFR) and ErbB2, which are overexpressed in many cancers." (PMID 39324018, 2024). "Targeted therapies have increased cancer therapy-related diarrhea (CTD) burden, with high incidence and/or severity of diarrhea for some agents that inhibit epidermal growth factor receptor and receptor tyrosine kinases." (PMID 38265977, 2024). "illustrated EMT responses to EGFR‐targeted chemotherapy, where treatment inhibited EMT‐driven cancer invasion by reducing vimentin levels and increasing E‐cadherin." (PMID 39101627, 2024). "The epidermal growth factor receptor (EGFR) is a tyrosine kinase receptor involved in cell proliferation, survival, and differentiation in both normal and cancer cells." (PMID 38249546, 2024). "Beyond the extensively studied RTKs such as epidermal growth factor receptor (EGFR) and vascular endothelial growth factor receptor (VEGFR), Axl has emerged as a promising target due to its role in cancer cell proliferation, migration, and invasion." (PMID 38675387, 2024). "Among the top 20 signatures identified from GSEA, several cancer‐related signatures, including the CCA signature and EGFR & KRAS signaling signatures, were significantly enriched in both cohorts." (PMID 38526177, 2024). "It functions by binding to the epidermal growth factor receptor (EGFR) and preventing cancer cell migration and invasion." (PMID 39399372, 2024). "In addition, the mechanism of action of bLF on cancer cell proliferation was investigated by determining the amount of phosphorylated intermediates of signaling pathways such as epidermal growth factor receptor (EGFR), extracellular signal‐regulated kinase (ERK) and protein kinase B (known as Akt)." (PMID 38726451, 2024). "GnT-III overexpression enhances ERK activation in several cancer cell lines, modifying RTK receptors such as EGFR and c-Met to enhance downstream signaling." (PMID 39571652, 2024).
cancer (continued). "AREG, a ligand for the epidermal growth factor receptor (EGFR), is known to play a critical role in the development and progression of various cancers, as well as in the resistance to radiation and chemotherapy." (PMID 39451251, 2024). "The treatment of pancreatic stellate cells—the progenitors of CAFs in PDAC—with TGF-β results in the marked upregulation of EGFR and HER2 activation, significantly enhancing the pro-metastatic capacity of myCAFs and promoting cancer cell metastasis in PDAC." (PMID 39770538, 2024). "Our study suggests that EGFR and DOCK4-mediated RAC1 activation in response to secreted brain endothelial factors oppose this contractile phenotype, allowing cancer cells to cross the endothelium and propel themselves into the brain parenchyma." (PMID 38762624, 2024). "Other options for targeted treatment include EGFR- or VEGF-dependent pathways, which are known to be overexpressed or dysregulated in this cancer type and are currently under clinical investigation." (PMID 38730642, 2024). "When cetuximab (an EGFR target inhibitor) was combined with avelumab (a PD-L1 target inhibitor) to treat NSCLC, the anti-cancer mechanism of these two antibodies partially depended on the activation of the ADCC and cGAS-STING pathways driven by NK cells." (PMID 39464890, 2024). "These genes were mostly enriched in biological processes, particularly in the PD‐L1 expression and PD1 checkpoint pathway in cancer, TNF signaling pathway, JAK–STAT signaling pathway, and epidermal growth factor receptor signaling pathway." (PMID 38627900, 2024). "Since malignancies are linked to overexpression of the human ErbB2 gene—which codes for the human EGFR, often known as HER2—id, the connection between ErbB2/HER2 and cancer has also been detected in humans." (PMID 39031216, 2024). "S6K1 signaling was constitutively activated in resistant cancer cells, and MDM2 was a functional effector of S6K1 in mediating EGFR-TKI resistance." (PMID 38397056, 2024). "Significantly, alterations in the structure or expression of EGFR can trigger tumorigenesis, and the EGFR-STAT3-PD-L1 pathway plays crucial roles in cancer growth and metastasis." (PMID 38785565, 2024). "Primary resistance, defined as the lack of initial responses to TKIs, has been observed in 20−30% of advanced EGFR‐mutant NSCLC patients, 20−40% advanced ALK‐positive NSCLC patients, 10% GIST patients, and other cancer patients." (PMID 39184861, 2024). "EnrichR pathway enrichment analysis coupled with Wiki Pathway datasets revealed pathways regulating multiple cellular processes that are commonly upregulated in cancers, such as VEGFA-VEGFR2 Signaling, PI3K-Akt signaling, and EGF/EGFR signaling." (PMID 38464090, 2024). "Further treatment with cordycepin in a mouse tumor model revealed reduced expression of Ki-67, p-EGFR, and p-STAT3 in cancer tissues." (PMID 39690423, 2024). "Combined targeting EGFR and MDM2 stabilize FBW7, as a result, accelerates prompt MCL-1 protein turnover and augments cancer cell apoptosis." (PMID 39543744, 2024). "When BSC was the control arm (the ‘later line’ trials), EGFR mAb therapy provided OS and PFS benefit in patients with KRAS WT cancers (OS HRadj 0.79, p = 0.036 and PFS HRadj 0.41, p < 0.001)." (PMID 38402342, 2024). "In conclusion, our study demonstrated that the natural product BA, a potential EGFR inhibitor, directly targets wt-EGFR and sensitizes innate TKI-resistant cancer cells to EGFR-TKIs." (PMID 38764025, 2024). "RHOV silencing inhibited proliferation and migration, as well as improved the sensitivity of EGFR-TKI and increased cancer cell apoptosis in gefitinib-resistant PC9 cells." (PMID 39478862, 2024). "Compound 1 of the series was found to be potent EGFR inhibitor with an IC50 value of 14.05 μmol/ml, it also displayed potent anticancer activity against HeLa cancer cell line with an IC50 value of 0.42 μM." (PMID 38605072, 2024).
cancer (continued). "As previous reports have suggested that miR200c reduces EMT in cancer cells through the regulation of ZEB-1, we aimed to investigate the role of miR200c in modulating the sensitivity of organoids to EGFR-TKIs." (PMID 39766891, 2024). "Vice versa, further studies need to evaluate the feasibility of using JAK-inhibitors to treat EGFR-inhibitor induced adverse events, as JAK-inhibitors are predicted to rather support cancer growth by blunting the activity of cytotoxic T-cells." (PMID 39521937, 2024). "Enhanced EGFR signaling via the MAPK pathway is commonly observed both in clinical settings and in cancer cell lines that have become resistant to endocrine therapies." (PMID 39850811, 2024). "Its primary objective was to evaluate the safety, tolerance, pharmacokinetics (PK), pharmacodynamics (PD), and anti-cancer effects of BLU-945, explicitly targeting the EGFR protein." (PMID 38927911, 2024). "The images of the cancer cells showed that HSY and A253 cells exposed to NIR-PIT using the EGFR Affibody–IR700Dye conjugate displayed morphological evidence of cellular bursting and bleb formation, whereas the morphology of MCF7 cells remained unchanged." (PMID 38542206, 2024). "As research progresses and clinical trials continue, abivertinib holds potential to provide renewed hope for patients with EGFR- and HER2-driven cancers." (PMID 38611728, 2024). "Compound V was detected to show anti-NSCLC effects and EGFR inhibition (IC50 = 32.5 nM), whereas compound VI inhibited both EGFR (IC50 = 0.009 μM) and HER2 (IC50 = 0.013 μM), and demonstrated potential antibreast cancer activity." (PMID 39780846, 2024). "EGF is a proinvasive factor that activates the EGFR-ERK pathway, leading to the induction of EMT of cancer cells, cancer cell invasion and metastasis." (PMID 39003350, 2024). "The ErbB family (EGFR, ErbB-3, and HER2) drives cancer proliferation and survival by activating Ras/MAPK, PI3K/Akt, and JAK/STAT pathways." (PMID 39138146, 2024). "EGFR signaling pathway plays crucial roles in cancer immune evasion, with SEC61G as an EGFR-coamplified gene promoting GBM immune evasion." (PMID 39105794, 2024). "Recent findings indicate upregulation of the epidermal growth factor receptor (EGFR) pathway, a key target in cancer therapy, by the spike protein of SARS-CoV-2." (PMID 39291996, 2024). "Alanazi and his team developed and evaluated a series of pyrimidine derivatives as multi-kinase inhibitors, including EGFR, VEGFR-2, CDK2, and HER2, besides the evaluation against a panel of cancer cell lines." (PMID 39404419, 2024). "The three phase I/II clinical trials use EGFR CAR-T cells expressing antibodies anti-PD-L1/CTLA-4, underscoring the utility of checkpoint inhibition in cancer immunotherapy (NCT03182816, NCT02873390, NCT02862028)." (PMID 38727261, 2024). "Thus, the EGF/EGFR signaling pathway may represent an important molecular target in cancer therapy." (PMID 39518052, 2024). "EGFR overexpression and activation were documented as an innate resistance mechanism to prexasertib in TNBC and potentially other cancers." (PMID 38539474, 2024). "As cytomembrane proteins, desmosomal cadherins and EGFR, a common receptor tyrosine kinase (RTK), have been reported to interact in several cancers previously." (PMID 38671389, 2024). "By cross-referencing these sources, we identified five top oncogenes—ALK, EGFR, GNAS, KRAS, and PIK3CA —due to their frequent occurrence and their critical roles in multiple cancers." (PMID 39684787, 2024).